IFNG (interferon gamma)
Diseases named in the same sentence as IFNG in open-access papers (continued):
Sharing a sentence is not in itself a finding about the gene and the disease.
tumor (continued). "When tumor bearing mice were treated with Salmonella + Alb-IL2, we observed increased frequencies of intra-tumoral CD4 and CD8 T cells as well as elevated levels of pro-inflammatory cytokines (IFNγ, TNFα, IL-2) in the tumor associated CD8 T cells." (PMID 35962391, 2022). "The endogenous IFNγ (encoded by IFNG), a cytokine strongly involved in natural tumor immune surveillance, was selected as an endogenous target." (PMID 35304449, 2022). "Tumor-specific resistance mechanisms include mutations in pathways such as the interferon gamma pathway, the MAPK pathway, and the PI3K/AKT/mTOR pathway." (PMID 36291789, 2022). "In early studies, the presence of TILs in tumours was associated to an increased PD-L1 tumour expression mediated by interferon gamma (IFN-γ)." (PMID 34683113, 2021). "Low levels of IFNG in the TME increase the risk of tumor metastasis during immunotherapy and are closely associated with poor prognosis in patients with NSCLC." (PMID 34487971, 2021). "A hot tumor is described as a tumor highly infiltrated by immune cells and frequently associated with high PD-L1 and interferon-γ (IFNγ) signature expression (and therefore, a priori, sensitive to anti-tumor immunity)." (PMID 34885109, 2021). "Of interest, after TIS, binding of soluble TSP1 to CD47 causes emergence of tumor-resistant cells and metastasis in triple-negative breast cancer, and inhibits anti-melanoma NK cell activity with reduced granzyme B and IFNγ production." (PMID 34447383, 2021). "Interferon-gamma (IFN-γ) producing Chinese Hamster Ovary cells (CHO-cells) are injected in mice and cause cachexia solely in the presence of IFN-γ and tumor cells." (PMID 34899373, 2021). "Correspondingly, the Topbp1MHC I-P30 vaccine elicited a significant antitumor benefit that was associated with the infiltration of IFNγ+ Topbp1MHC I-specific TILs into the tumor." (PMID 33462231, 2021). "There are several common biomarkers of immune-checkpoint inhibitor (ICI) under evaluation, including tumor-infiltrating lymphocytes (TIL), interferon gamma (IFN-γ), and tumor mutational burden (TMB)." (PMID 34442426, 2021). "High levels of all the evaluated parameters (interferon-gamma gene expression signature, tumor mutational burden, and CD8+ T-cell infiltration by IHC) showed an association with improved RFS for both nivolumab and ipilimumab." (PMID 33925387, 2021). "The MHC-II is the critical component of adaptive anti-tumor immunity, and its upregulation is closely associated with increased levels of interferon-gamma in tumors." (PMID 34899864, 2021). "It directly inhibits the hallmark of cytotoxic T cell anti-tumour immunity by suppressing perforin, granzyme A, granzyme B, Fas ligand and interferon-gamma (IFN-γ) production." (PMID 34771746, 2021). "In contrast, IFNγ was shown to induce PD-L1 expression on tumor cells, reducing their susceptibility to NK cytotoxicity." (PMID 33801234, 2021). "IFNG is an important macrophage activator which has a regulatory effect on the phenotypic transformation of tumor-associated macrophages and can resist the growth of pancreatic tumors." (PMID 34868262, 2021). "Defects in IFNγ signaling cause resistance to T cell-mediated tumor killing in both pre-clinical models and cancer patients." (PMID 33446805, 2021). "At the molecular level, cytokines IL-1, IL-6, and tumor growth factor-beta (TGFβ) are associated with tumor progression, whereas IL-12 and interferon-gamma (IFNγ) can inhibit cancer proliferation and/or metastasis." (PMID 34680134, 2021). "IFNγ exposure can also result in autophagy-associated apoptosis of tumor cells via activation of cytosolic phospholipase A2-dependent production of mitochondrial reactive oxygen species." (PMID 33801234, 2021). "Splenocytes from mRIPO-treated animals provoked varied tumor-specific lymphocyte states as evidenced by expanded baseline and antigen-specific Th1- (IFNγ, TNF), Th2- (IL-5), and Th9- (IL-9) associated cytokine secretion." (PMID 33767151, 2021).
tumor (continued). "As observed in C57BL/6 mice implanted with the MCA205 murine fibrosarcoma cell line, NK cell depletion and IFNγ deficiency allowed for an increased tumor growth compared to the control mice." (PMID 34960234, 2021). "A concerted action of IFNβ and IFNγ upregulates Gal-9 expression in APCs (B cells, dendritic cells, and tumor-associated macrophages) and cancer cells and its secretion from these cells to dampen antitumor response by inducing T cell death." (PMID 33547304, 2021). "In contrast, tumors infiltrated by CD8 T cells often demonstrate higher MHC-I expression compared to the adjacent tissue, an increase that has been linked mechanistically to IFNγ secreted by activated T cells in the tumor microenvironment." (PMID 34201655, 2021). "Accordingly, expression of genes encoding IFNγ, CD8α and CD8β was significantly increased in tumor samples with a low TSP1 expression." (PMID 34439212, 2021). "Similar findings were observed in a melanoma model, where Trichostatin A induced MHC-I expression promoting IFNγ production by T cells specific for a tumor-associated antigen." (PMID 33859645, 2021). "Interferon γ (INF-γ), encoded by IFNG gene, has antiviral, immunoregulatory, and anti-tumor properties in the immune system and is secreted by mostly T cells and NK cells." (PMID 33757216, 2021). "Resistance to checkpoint blockade was found to be associated with genomic defects in the IFNγ pathway in tumor cells." (PMID 34438367, 2021). "Decreased IFNg induction or signal has also been demonstrated to be associated with increased sensitivity to intracellular bacteria, some viruses and tumor onset." (PMID 33237662, 2021). "These investigators described a disrupted IFNγ-JAK-STAT signaling cascade in Tet2-deficient tumor cells that we also found with β cells." (PMID 34417463, 2021). "MEK inhibition was associated with an increase in CD8+ T-cell infiltration of tumors, elevated interferon-gamma (IFN-γ) gene expression signatures, as well as a decreased presence of tumor-associated macrophages and regulatory T cells." (PMID 33275172, 2021). "IFNγ is an effector cytokine, associated with antitumor mechanisms, which include increased tumor immune surveillance, and antiproliferative, pro-apoptotic tumor mechanisms." (PMID 34943886, 2021). "Mechanistically, the lack of Treg expansion observed in the tumor microenvironment is mediated by CD8+ T‐cell‐associated cytokines, including IFNγ and TNFα, which are released in response to cognate tumor antigen recognition in the tumor tissue." (PMID 33152115, 2021). "Interferon gamma (IFNγ) is a hallmark cytokine produced by tumor infiltrating lymphocytes, such as NK and T cells, and its activation of TAMs leads to tumor inhibition through multiple mechanisms." (PMID 33976173, 2021). "It is important to consider that IFNγ treatment mimics the phenotype of a “hot” tumor, a phenotype associated with improved immunotherapy success." (PMID 33968037, 2021). "IFNg can induce the fragility of tumor-derived T-regs, the loss of T-reg suppressive activity, and the inhibition of T-reg expansion." (PMID 34835178, 2021). "In hepatocellular carcinoma, combined anti-CTLA-4 and PD-1 together with the HDACi Belinostat significantly reduced tumor burden; which was associated with increased IFNγ production by T cells, and decreased amounts of Treg." (PMID 33859645, 2021). "In a study focused on tumor-associated neutrophils, the authors also used LPS and IFNγ/IFNβ to derive N1 neutrophils and a much more complex mediator cocktail to derive N2 cells." (PMID 34447377, 2021). "In support of this, an IFNγ-driven T-cell inflamed gene expression profile is associated with improved response to PD-1 blockade with pembrolizumab across multiple tumour types." (PMID 34740105, 2021). "Higher tumor mutation burden, interferon-gamma gene expression, and DNA damage repair alterations have also been associated with response rates but require additional validation." (PMID 31811337, 2020).
tumor (continued). "IL-12 conditioning caused downregulation of IFNγR2 with a concomitant decrease in susceptibility to IFNγ-induced apoptosis of tumor-infiltrating CD8+ T cells." (PMID 33178203, 2020). "Our current study clearly demonstrates that a significant fraction of tumor-specific CTLs have hypermethylation at the IFNγ promoter and IFNγ deficiency." (PMID 32194559, 2020). "We employed an isogenic murine RCC model to investigate the impact of PBRM1 loss on tumor-autonomous IFNγ signaling and on the TME, measured the effect of PBRM1 loss on response to ICB, and validated our findings in human ccRCC datasets." (PMID 32358509, 2020). "This even leads to a dominant, Treg-cell-intrinsic anti-tumor function, as the sole transfer of Carma1-deficient Treg cells into immunocompetent recipients, is sufficient to reduce tumor growth in an IFNγ-dependent manner." (PMID 33143070, 2020). "LINC000426 is associated with IFNG transcription and the activities of tumor infiltrating CD8+ T cells, hence LINC000426 expressing tumors are more sensitive to Dexamethasone." (PMID 33194770, 2020). "Altogether, we propose that a sizeable portion of human tumor-specific CTLs are deficient in IFNγ response, contributed by CpG hypermethylation of the IFNγ promoter." (PMID 32194559, 2020). "Flow cytometry analysis of tumor-infiltrating CD8s revealed that YAP-deficient cells produce more IFNγ and TNFα." (PMID 32322254, 2020). "PBAF-deficient tumor cells produce more chemokines in response to IFNγ, promoting cytotoxic T cell functions." (PMID 35582435, 2020). "Such IFNγ signaling-deficient cancer cells required cooperation from IFNγ signaling-sufficient and PD-L1-positive cells for immune escape, indicating the importance of PD-L1 and environmental clues for tumor immune escape." (PMID 32992658, 2020). "SHP-1 deficient CAR19 T cells also secreted more IFNγ, TNFα, and IL-2 and these T cells were more efficient in killing tumor cells in vitro and in vivo." (PMID 33425916, 2020). "While IFNγ signaling in tumor cells leads to upregulation of PD-L1, transporter associated with antigen processing (TAP1), MHC class I and T cell chemotaxis factors, as well as IFN-induced growth inhibition, IFNγ is also a key regulator of DCs and macrophages." (PMID 32273348, 2020). "Rather, this group suggested that inhibition of angiogenesis mediated by IFNγ production causes massive tumor necrosis." (PMID 33178203, 2020). "Altogether, these observations suggest a strong association between IFNγ promoter CpG hypermethylation with an impaired IFNγ-mediated response in human tumor-specific CTLs." (PMID 32194559, 2020). "Next, we provide evidence that combined anti-PD-1/G007-LK treatment of B16-F10 tumors is effectuated by G007-LK-induced loss of β-catenin in the tumor cells and induction of an interferon-γ (IFNγ)- and CD8+ T cell-dependent anti-tumor-immune response." (PMID 32332858, 2020). "The pre-existence of intratumor T cells, ICPi, and IFNγ-related immune signature accounts for an ‘inflamed’ tumor microenvironment, which is usually associated with a positive response to ICPi therapy." (PMID 32707692, 2020). "Mechanistically, CBM- and Rel-deficient Treg cells exhibit impaired expression of aTreg-associated genes and accumulation in tumor tissues, while significantly increasing their expression of Tconv-associated markers, in particular IFNγ." (PMID 33143070, 2020). "A decline in the CD56 dim NK are observed in circulating blood and in HCC tumour nodules, which suggests that the suppressed tumour-surveillance functions of NK cells is caused by a decline in the release of IFNγ and cytotoxic activity in HCC patients." (PMID 32466214, 2020). "In particular, CD4 TH1 cells characterized by the secretion of IFNγ (Interferon gamma)-associated cytokines can not only contribute to direct tumor cell killing but also endow CD8 T and NK (natural killer) cells with optimal cytotoxic functions." (PMID 32707692, 2020).
tumor (continued). "To further confirm that the IFNγ defect is associated with tumor-specific CTLs, we assessed and compared the IFNγ transcription kinetics in the ex vivo isolated short-term expanded tumor-specific and virus-specific CTL lines." (PMID 32194559, 2020). "During the process of accessing the tumor purity, higher TMEscore was associated with a good prognosis and characterized by the response to virus and IFNγ that was consistent with the features of MSI in latest researches." (PMID 32850385, 2020). "Flowcytometry results showed that Atrx deficiency increase the penetration of CD3+ T cell into the tumor microenvironment and enhanced antigen presentation after IFNγ stimulation." (PMID 33409155, 2020). "In MHC deficient tumor-cells, pretreatment with IFNγ is required to express the antigen processing machinery and the class I MHC complex." (PMID 35582435, 2020). "The cytotoxic CD8+ T cell population, supported by CD4+ T helper (Th1) cells through the production of IL2 and IFNγ, generates the final effector mechanism leading to tumor elimination and are associated with a good prognosis." (PMID 32423420, 2020). "IL-10 is secreted in the TME and it has been shown to induce an exhausted phenotype on tumor infiltrating T cells characterized by low proliferation and suppressed secretion of cytokines associated with an effector phenotype as IL-2, IFNγ and TNFα." (PMID 32937953, 2020). "Here, the authors show that PBRM1 loss reduces IFNγ-mediated signalling resulting in a less immunogenic tumor microenvironment and that PBRM1 mutations correlate with lack of response to checkpoint inhibitor therapy in ccRCC patients.." (PMID 32358509, 2020). "In summary, combined anti-PD-1/G007-LK treatment of B16-F10 tumors is dependent on tankyrase inhibitor-mediated loss of β-catenin in the tumor and induces an IFNγ and CD8+ T cell-dependent growth-inhibitory effect." (PMID 32332858, 2020). "The first one, IFNγ, is associated with an anti-tumor response and is an inflammatory marker in the elimination of the tumor." (PMID 32733470, 2020). "IFNγ—initially associated with tumor immunity also enhances the activation of the PD-1 signaling axis." (PMID 33087163, 2020). "We observed that ARV-p10 expression resulted in syncytium formation associated with a cytotoxic effect in vitro, and intratumor treatment with NP-ARV caused a mild delay in tumor development associated with an increase in splenic Th1+ IFNγ+ lymphocytes." (PMID 32626742, 2020). "The anti-tumor efficacy of this Lipid A has previously been demonstrated in several models of tumors and was dependent on cytokine secretion (IFNγ, IL-1β and TNFα), iNOS activation and tumor-associated neutrophil (TAN) reprogramming into anti-tumorigenic N1." (PMID 32370259, 2020). "CCL4 and IFNγ, inflammatory markers associated with tumor progression, were also reduced with PFD treatment." (PMID 31492002, 2019). "Global loss of IFNγ is detrimental to tumor surveillance in mice, as Ifnγ−/− mice develop tumors more quickly than their Ifnγ+/+ counterparts in the setting of carcinogen-induced or spontaneously arising tumors." (PMID 31133614, 2019). "The growth of primary tumours and metastases is strongly inhibited in C3-deficient mice and is associated with increased numbers of IFNγ+/TNFα+/IL10+ CD4+ and CD8+ T cells." (PMID 30841875, 2019). "While the intrinsic mechanism leads to PD-L1 expression after oncogenic mutation, the adaptive mechanism causes tumor cells to express PD-L1 after they have been stimulated by interferon gamma secreted by CD8+ T cells." (PMID 30668545, 2019). "In mouse models, loss of IFNγ signaling accelerated tumor initiation and progression, demonstrating a direct impact of IFNγ signaling on tumorigenesis, the tumor microenvironment and metastatic dissemination." (PMID 31552026, 2019). "Further analysis revealed that suppression of IFNγ is caused by BACH2-mediated Treg-dependent tumor immunosuppression." (PMID 31824865, 2019).
tumor (continued). "We confirmed that MET-amplified tumours are susceptible to the inducible expression of PD-1 ligands by IFNγ." (PMID 30723303, 2019). "In support of this conclusion, Hepa1-6 tumors in chemerin-/- mice displayed increased proportions of MDSCs, tumor-associated macrophages (TAMs) and decreased IFNγ-expressing T-helper CD4+ and cytotoxic CD8+ T cells compared to Hepa1-6 tumors in wild-type mice." (PMID 31561459, 2019). "We thus assume that the differentiation of TAMs selectively observed in OVA expressing B16F10/M2KO/OVA tumors was caused by IFNγ released from CD4+ Th1 cells as a consequence of tumor antigen-specific TAM / CD4+ Th1 interaction in vivo." (PMID 30853959, 2019). "In the multi-tumor cohort, several signatures were associated with response, but only IFNγ signature remained significant after adjusting for TIS (p-value = 0.03); whereas TIS, immunoproteasome, lymphoid and hypoxia signatures were predictive of survival." (PMID 31684954, 2019). "Programmed death ligand 1 (PD-L1), a T cell inhibitory molecule, is upregulated in response to interferon gamma and associated with a T cell-inflamed tumor microenvironment." (PMID 30857555, 2019). "These mutations impair recognition of the tumor by the adaptive immune system, either by directly disrupting antigen presentation or by rendering the cells insensitive to IFNγ, an important inducer of MHC-I expression." (PMID 31452512, 2019). "Accordingly, the myeloid cell's Trim24 deficiency impaired the tumor infiltration of IFNγ-producing CD4+ and CD8+ effector T cells, suggesting that Trim24 deficiency impaired antitumor immunity through suppressed Stat6 acetylation in TAMs." (PMID 31554795, 2019). "Further, Tregs can indirectly hamper CD8+ T cell activation by restraining expansion and immunogenicity of tumor-associated dendritic cells (DCs), leading to reduce IFNγ secretion and poor tumor control, as seen in an orthotopic pancreatic cancer model." (PMID 30917934, 2019). "The two tumor proteins (Flt-3L, IFNγ) positively associated with muscle weight and TFBW both had negative correlations with all atrophy related gene expression." (PMID 30513792, 2018). "Despite the absence of CAR T cells, incubation of splenocytes from long-term survivor CAR-IL-12-treated (C12T) mice with A20 tumor cells showed the presence of reactive T cells by IFNγ enzyme-linked immunospot (ELISpot)." (PMID 29367945, 2018). "T helper 1 (Th1) T cell responses are associated with tumor suppression and upregulation of IFNγ and IL-12, while T helper 2 (Th2) responses are reliant of IL-4 production and exhibit protumor activity." (PMID 29463044, 2018). "The enhanced checkpoint blockade responsiveness in DIO mice was associated with significantly increased CD8+ tumor- infiltrating lymphocytes (TILs), as well as increased TNFα and IFNγ-production by CD8+ T cells." (PMID 30400822, 2018). "Mechanically, LNT inhibited tumor angiogenesis via IFNγ up-regulation, which was associated with the accumulation of tumor-infiltrating myeloid cells." (PMID 30373628, 2018). "It came out that carriers of the MTHFR-rs1801131-CC or IFNG-rs1861494-AG/GG genotype had the worst prognosis than all the rest of the patients and this was independent from the other risk factors, including tumor stage." (PMID 30337874, 2018). "Tumor intrinsic mechanisms include downregulation or loss of antigens and antigen presentation molecules, disruption in the IFNγ signaling pathway and T cell exclusion." (PMID 29968076, 2018). "A similar study with 8 patients treated with IP IFNγ found similar rises in tumor associated lymphocytes and macrophages, 1 patient with a complete response, 2 with partial responses and 2 with stable disease." (PMID 30012146, 2018). "The secretion of IL18 and IL22 by TAMs has also been associated with tumor cell killing as they can amplify cytokine production (particularly IFNγ and IL2) and by augmenting the cytotoxic activity of NK cells." (PMID 29594035, 2018).